C4BPA (complement component 4 binding protein alpha)
Diseases named in the same sentence as C4BPA in open-access papers (continued):
Sharing a sentence is not in itself a finding about the gene and the disease.
tumor (16 papers, 2007 to 2025). "Higher abundance of C4b-binding protein, particularly the alpha chain (C4BPA), has been associated with enhanced antitumor immunity in the PDAC tumor microenvironment." (PMID 41007761, 2025). "This aligns with findings from recent research demonstrating that C4BPA plays a critical role in promoting the accumulation of CD8 + tumor-infiltrating lymphocytes and enhancing the tumor microenvironment to counteract cancer progression." (PMID 39775340, 2025). "It has been reported that stimulation with murine C4BPA peptide increased the number of CD8+ tumor-infiltrating lymphocytes surrounding PDAC tumors in vivo and high stromal C4BPA was associated with favorable PDAC prognosis." (PMID 37628784, 2023). "The sequestration of plasma regulators, such as C4BPA, by tumor cells has been shown as a mechanism to prevent complement-dependent cytotoxicity." (PMID 35800053, 2022). "The result showed that the lower mRNA expressions of C3, C5, CFB, and CLU were correlated with more advanced cancer stage, while the lower mRNA expressions of C1S, C8B, CFI, MBL2, and C4BPA were correlated with higher tumor grade in HCC patients." (PMID 34813686, 2022). "Next, to assess the in vitro effects of C4BPA on tumor cell proliferation that are exerted via CD40, we examined PDAC cell proliferation with CD40 knockdown." (PMID 34167573, 2021). "In addition, the mRNA expressions of C1S, C8B, MBL2, CFI, and C4BPA were correlated with tumor grade and prognosis in HCC patients." (PMID 34813686, 2022). "New research indicated that high levels of stromal C4b binding protein alpha chain (C4BPA) within human PDAC tissue were associated with better prognosis, including longer OS, and strongly correlated with increased levels of CD8+ tumour-infiltrating lymphocytes." (PMID 34638318, 2021). "Herein, we hypothesized that C4BPA exhibits an antitumor T cell response with the accumulation of tumor-infiltrating lymphocytes (TILs) via the C4BPA-CD40 axis in PDAC." (PMID 34167573, 2021). "This highlights C4BPA stimulation as another potential method that could convert PDAC to an immunologically ‘hot’ tumour and thus increase the curative potential of ICIs." (PMID 34638318, 2021). "Stromal C4BPA strongly correlated with the number of CD8+ tumor-infiltrating lymphocytes (P=0.001)." (PMID 34167573, 2021). "We hypothesized that C4BPA may also affect the tumor cell itself in PDAC." (PMID 34167573, 2021). "We assessed stromal C4BPA, the C4BPA binding partner CD40, and the number of CD8+ tumor-infiltrating lymphocytes in resected human PDAC tissues via immunohistochemical staining." (PMID 34167573, 2021). "C4BPA was not expressed in the PDAC tumor cells but was predominantly expressed in the stroma surrounding the PDAC cells." (PMID 34167573, 2021). "Here, we elucidated the functional roles of C4BPA in PDAC cells and the tumor microenvironment." (PMID 34167573, 2021). "C4BPA and PLA2G1B showed the most positive (19.8) and negative (0.009) fold changes in gene expression, respectively, when comparing Group B1 differentially expressed mRNA in the post-chemotherapy tumor bed to Group A." (PMID 39249118, 2024).
cancer (11 papers, 2021 to 2025). A tumor composed of atypical neoplastic, often pleomorphic cells that invade other tissues. "The same study found that C4BPA mutations are associated with improved cancer survival outcome." (PMID 37817005, 2024). "Among the downregulated proteins, paraoxonase 1 (PON1), which protects against oxidative stress, and C4BPA, which inhibits cancer progression by promoting antitumor T cells, are notable." (PMID 41271007, 2025). "A cancer cell line study demonstrated that C4BPA was expressed intracellularly in cancer cells and interacts with the NF-κB family member RelA and regulates apoptosis." (PMID 37817005, 2024). "Contrary to the cancer-promoting functions of complement in tumors, we demonstrate that C4BPA mediates the recruitment of CD8+ TILs, presenting cancer-suppressive functions in the TME of PDAC." (PMID 34167573, 2021). "Furthermore, C4BPA increases the chemosensitivity of Gem by inducing apoptotic programmed cancer cell death." (PMID 34167573, 2021). "Immunohistochemistry results indicated significantly elevated GALP, CACNA1C, COL16A1, PENK, C4BPA, PSMA2, and CXCL9 expression in cancer tissues." (PMID 38481252, 2024). "Immunohistochemistry results indicated significant upregulation of GALP, CACNA1C, COL16A1, PENK, C4BPA, PSMA2, and CXCL9 in cancer tissues." (PMID 38481252, 2024).
infection (7 papers, 2011 to 2025). The state of being infected such as from the introduction of a foreign agent such as serum, vaccine, antigenic substance or organism. "In comparison, C4BPA an inhibitor gene associated with the classical complement pathway was down-regulated in the asymptomatic (resilient to infection) dataset." (PMID 30709726, 2019). "In the clinical phase of infection, proteins such as prothrombin (fragment), complement component 4 binding protein alpha, and alpha-2-macroglobulin are upregulated, indicating an immune response." (PMID 40646861, 2025). "Moreover, C3, C5, C2, C1S, C4BPA (genes involved in the complement pathway) and SERPING1 (a regulator of complement activation) were significantly up-regulated, indicating an important role of the complement pathway in this infection." (PMID 34203742, 2021). "In particular, some genes involved in immune/inflammatory responses and infection (e.g., IL19, MAPK15, and SERPINB10) and components of a complement system (e.g., C4B, VTN, BDKRB1, and C4BPA) have not been previously reported regarding their expression and functions in human omental adipose tissue." (PMID 30816281, 2019).
heart disease (1 paper, 2023). "Although APP and C4BPA are associated with heart disease, we showed that these recurrent FBI polymorphisms in the two genes were non-causative factors of CHD." (PMID 37684230, 2023).
C4BPA also shares sentences with these, for which no sentence is quoted: bipolar disorder (2 papers); metabolic disorder (2); Alzheimer disease (1); amyloidosis (1); cardiovascular disease (1); cervical cancer (1); chronic kidney disease (1); chronic pancreatitis (1); cognitive decline (1); dental caries (1); depression (1); diabetes (1); Duchenne muscular dystrophy (1); epithelioid mesotheliomas (1); gastric cancer (1); Hepatic steatosis (1); Intellectual disability (1); irritable bowel syndrome (1); ischemic stroke (1); lung adenocarcinoma (1); neurodevelopmental disorder (1); oral candidiasis (1); pancreatitis (1); primary immunodeficiency (1); Respiratory tract infection (1); staphylococcus aureus infection (1); thyrotoxicosis (1).